MYC (MYC proto-oncogene, bHLH transcription factor)
Diseases named in the same sentence as MYC in open-access papers (continued):
Sharing a sentence is not in itself a finding about the gene and the disease.
multiple myeloma (continued). "Vκ*MYC has also impacted the field of myeloma immunotherapy in more ways than one." (PMID 34149703, 2021). "Exon 3 in MYC is highly conserved across species and, interestingly, hypomethylation at MYC exon 3 was observed in human myeloma cell lines compared to normal lymphocytes and correlated with progression from normal tissue to metastatic disease in colorectal tissue." (PMID 33374332, 2020). "A key aspect of the mTORi/HDACi combination is its ability to decrease MYC protein stability; however, in some myeloma cell lines, we have observed a “compensatory” MYC mRNA increase with combination treatment, although the steady-state protein level is decreased." (PMID 32923678, 2020). "Using a small molecule microarray, we found a selective MYC-G4 binding drug with a benzofuran scaffold (D089) that not only inhibited MYC expression in myeloma cell lines, but also selectively induced G1 arrest in MYC-driven cancer cell lines containing the MYC-G4 sequence." (PMID 33066043, 2020). "In conclusion, ITGA9 was a vital cell adhesion molecule in myeloma which may be negtive regulated by MYC." (PMID 32581652, 2020). "GSEA results showed that ITGA9 was a vital cell adhesion molecule and may be repressed by MYC in myeloma." (PMID 32581652, 2020). "Maintaining c-MYC levels is important for the survival of myeloma cells." (PMID 32235336, 2020). "This suggests that c-MYC/IRF4/miR-125b interplay could be less effective in NB compared with multiple myeloma in terms of MICA induction." (PMID 31040907, 2019). "Moreover, JQ1 increased the expression of MICA in multiple myeloma, since the downregulation of c-MYC leads to up-modulation of miR-125-5p and the consequent downregulation of its target gene IRF4, known as transcription repressor of MICA." (PMID 31040907, 2019). "In multiple myeloma, MYC is up-regulated and leads to development of the malignant phenotype." (PMID 29472861, 2018). "In addition to bladder cancer, FGFR3 translocations and amplification of the CCND1 and MYC genes are common in multiple myeloma." (PMID 29423038, 2018). "In myeloma, MYC activation may be mediated through copy number changes or translocations where B-cell super-enhancers are juxtaposed to MYC, thus resulting in its overexpression." (PMID 29228738, 2017). "Here we further dissect the anti-myeloma mechanisms mediated by EZH2 inhibition and show that pharmacological inhibition of EZH2 reduces the expression of MM-associated oncogenes; IRF-4, XBP-1, PRDM1/BLIMP-1 and c-MYC." (PMID 28052011, 2017). "The Vk*MYC mouse model has been established as an investigative tool for anti-myeloma drug therapy." (PMID 27599546, 2016). "We reasoned that CBP/EP300 bromodomain inhibition may exert its phenotypic effects through the suppression of MYC downstream of IRF4 in multiple myeloma cells." (PMID 26731516, 2016). "While BET proteins are known to similarly target MYC in multiple myeloma, a comparison of CBP/EP300 and BET bromodomain inhibition demonstrated that these modalities target the IRF4-MYC network at different nodes, with BET inhibition having no impact on IRF4 at the doses and timepoints examined." (PMID 26731516, 2016). "Reduced expression of IRF4 in people carrying the rs872071 G allele should lead to reduced expression of BLIMP-1, which, given the function of BLIMP-1 as a MYC repressor, could help in abnormal growth of MYC expression during the formation of multiple myeloma." (PMID 28083618, 2016). "In multiple myeloma, elevated MYC expression is related to disease initiation and progression." (PMID 26087190, 2015). "We also treated the primary myeloma samples with the MYC inhibitor to obtain IC50 values." (PMID 26087190, 2015). "When isolating primary myeloma cells from bone marrow samples the procedure usually takes a few hours and there is a risk that MYC protein and mRNA levels are not maintained at the same levels as when the cells are situated in the bone marrow." (PMID 26087190, 2015).
multiple myeloma (continued). "We wanted to find out if the baseline MYC expression could determine myeloma cell sensitivity to 10058-F4." (PMID 26087190, 2015). "We hypothesized our novel finding of down-regulated AR and AR-V expression following JQ1 treatment represented an important component of the JQ1 anti-AR mechanism of action, reminiscent of down-regulated MYC expression in multiple myeloma cells." (PMID 25908785, 2015). "And thirdly, MYC expression was in the same range in plasma cells from untreated compared to treated patients indicating that MYC activation is an early oncogenic event in multiple myeloma." (PMID 26087190, 2015). "Interestingly, the MYC mRNA levels were not different between previously treated and untreated patients, indicating that untreated patients had myeloma cells with as high MYC expression as patients in later stages of disease." (PMID 26087190, 2015). "MYC activation also seems to play a role in the progression of plasma cell neoplasms particularly from monoclonal gammopathy of undetermined significance (MGUS) to plasma cell myeloma (PCM)." (PMID 26416427, 2015). "To summarize, our results suggest that many myeloma patients, but first of all patients with cells expressing high MYC levels, might benefit from MYC inhibition." (PMID 26087190, 2015). "More recently, it was shown that the MYC pathway is activated in majority of myeloma patients and may be an important transforming event from MGUS to MM." (PMID 25101266, 2014). "Furthermore, targeting MYC using short hairpin RNA or a selective small molecule inhibitor of MYC-Max heterodimerization (10058-F4) induced myeloma cell death." (PMID 24252328, 2013). "Overexpression of MYC leads to the development of myeloma phenotypes in the Vk*MYC mouse model." (PMID 24252328, 2013). "Notably, tasquinimod induced apoptosis in JAK2V617F cells, both in vitro and in vivo, corroborating similar findings in multiple myeloma and acute myeloid leukemia where tasquinimod, especially in combination with venetoclax, led to reduced MYC targets, cell cycle regulators, and mTORC1 signaling." (PMID 40823315, 2025). "Clinical myeloma defining end organ damaging events (CRAB: renal impairment, anemia, bone disease) occur only after long latency (usually 70 weeks of age), suggesting that additional mutations, beside MYC dysregulation, are required to induce full malignant transformation." (PMID 38714690, 2024). "Thus, we link proteolytic ubiquitylation with post‐transcriptional regulation and nominate OTUD6B as a potential mediator of the MGUS‐multiple myeloma transition, a central regulator of MYC, and an actionable vulnerability in multiple myeloma and other tumors with an activated OTUD6B‐LIN28B axis." (PMID 36059274, 2022). "Hence, each mouse was injected with a total of 200 000 Vκ*MYC myeloma cells." (PMID 36435864, 2022). "In addition, a recent report suggests that patients with elevated c-MYC expression show enhanced sensitivity to proteasome inhibitors in relapsed/refractory multiple myeloma, indicating that c-MYC might be a clinically relevant target of proteasome inhibition." (PMID 36846090, 2022). "The treatment of multiple myeloma cells with the BRD4 inhibitor JQ1 resulted in the loss of BRD4 at the majority (90%) of promoters and more than half (60%) of the enhancer regions with a preferential loss of BRD4 at super-enhancers of key oncogenic drivers such as c-MYC." (PMID 34333666, 2021). "Thus, the amplification of MYC generates high levels of replicative stress and ROS, with the consequence that myeloma cells harboring this translocation could be attacked with combinations of agents that block the stress response." (PMID 33562668, 2021). "Many myeloma mouse genetically engineered models have focused on the dysregulation (overexpression or knock-out) of a particular gene or pathway, most notably, the dysregulation of MYC or BCL2, as well as the earlier spontaneous 5T models that have M spikes and develop bone lesions." (PMID 32923678, 2020).
multiple myeloma (continued). "MYC is among the most consistently upregulated genes in new myeloma and its overexpression frequently becomes “hard wired” in the course of tumor progression due to illegitimate genetic rearrangements such as complex chromosomal translocations and indels at the MYC locus." (PMID 31139207, 2019). "MYC structural variants are pervasive in B cell malignancies and myeloma is no exception." (PMID 31231360, 2019). "Importantly, the ligand inhibited c-MYC transcription and reduced cell viability in a panel of myeloma cell lines, whereas it exhibited minimal effects for a cell that harbors a c-MYC translocation, deleting the G4-forming element in the promoter and normal blood mononucleocytes." (PMID 30682877, 2019). "Thus MYC-dependent miR-23b repression in myeloma cells may promote activation of oncogenic Sp1-mediated signaling, representing the first feed-forward loop with critical growth and survival role in myeloma." (PMID 26771806, 2016). "Similar with I-BET762, I-BET151 also inhibits myeloma cell proliferation through inducing apoptosis and exerting strong anti-proliferative effect in vitro and in vivo through transcriptional repression of MYC and MYC-dependent programs by abrogating recruitment to transcriptional activator PTEFb." (PMID 25849938, 2015). "Thus, elevated MYC expression is achieved differently in myeloma cell lines and primary cells." (PMID 26087190, 2015). "Thus, we hypothesize that patients with myeloma cells expressing high levels of MYC could benefit from MYC inhibition." (PMID 26087190, 2015). "However, MYC rearrangements and activation occur more commonly in hyperdiploid myeloma." (PMID 25101266, 2014). "EBV-positive patients typically exhibit intact MYC due to alternative oncogenic factors such as JAK-STAT activation, whereas myeloma-like MYC-driven aggressive metabolism often prevails in EBV-negative PBL." (PMID 40563566, 2025). "In multiple myeloma, low CD302 expression activates oncogenic MYC pathways, driving disease progression and poor prognosis, while high expression correlates with prolonged overall survival (OS)." (PMID 41323386, 2025). "In Multiple Myeloma, ETV4-dependent transcriptional plasticity can maintain MYC expression and is related to drug resistance." (PMID 41318472, 2025). "Whereas the IGH-multiple myeloma gene signature was most notable for elevated IGH, the LCE-multiple myeloma signature contained biologically intriguing transcript elevations including LAMP5 and MYC." (PMID 39699274, 2025). "In a case report, a patient with rapid progression and poor prognosis was identified as having double‐hit multiple myeloma, characterized by both IgH/CCND1 and IgH/MYC translocations." (PMID 40859868, 2025). "In multiple myeloma, JQ1 also inhibits the interaction between dysregulated BRD4 and igG enhancers within the MYC locus, suppressing MYC and its downstream signals." (PMID 39934895, 2025). "The researchers conjugated anti-CD63 monoclonal antibodies with siRNA using arginine linkers to target the mRNA transcripts of MYC and CTNNB1 genes in human multiple myeloma cells (OPM-2)." (PMID 39355533, 2024). "MYC and IRF4 form an autoregulatory circuit in multiple myeloma, where they induce each other’s transcription to promote MM cell growth and survival." (PMID 38911853, 2024). "The PROTAC ARV-825 was antiproliferative in a panel of 13 multiple myeloma (MM) cell lines, led to cell cycle arrest and apoptosis, and quickly degraded BRD2 and BRD4 accompanied by suppression of MYB and MYC." (PMID 38835346, 2024). "According to the TOURMALINE-MM1 trial, ixazomib, LEN, and dexamethasone improved PFS compared with Rd in patients with myeloma and a high expression of the c-MYC gene, although LEN-refractory myeloma patients were excluded from this trial." (PMID 38004369, 2023). "IRF4 activate c-Myc expression, and IRF4 was itself a direct target of MYC transactivation, generating an autoregulatory circuit in myeloma cells." (PMID 35338347, 2023).
multiple myeloma (continued). "In the research of multiple myeloma, targeting an MDM2/MYC axis can trigger remarkable apoptosis and overcome drug resistance." (PMID 37291112, 2023). "The siRNA drug DCR-MYC, designed by Dicerna Pharma, is a novel synthetic dsRNA in a stable lipid particle suspension that targets MYC in HCC, solid tumors, and multiple myeloma." (PMID 36918935, 2023). "Inhibition of Class I HDACs by HDACi or in combination with the immunomodulatory drug Lenalidomide, resulted in the downregulation of cellular Myc proto-oncogene protein (c-MYC) and increased cytotoxicity in multiple myeloma cells." (PMID 36012642, 2022). "KDM5A coexists with MYC and the components of the transcriptional machinery, including CDK7, CDK9, and RNAPII, across the genome of multiple myeloma cells." (PMID 35805040, 2022). "This process is described as an autoregulatory circuit in myeloma cells, with IRF4 directly targeting MYC while also serving as a direct target of MYC transactivation." (PMID 35406421, 2022). "We illustrate a relationship between high OTUB1 expression and decreased survival in multiple myeloma, a c-MYC-dependent cancer, and confirm the ability of OTUB1 to stabilize c-MYC in a multiple myeloma cell line." (PMID 35159073, 2022). "Considering the critical role of MYC in driving tumor growth and relapse in hematological cancers, the effects of TCH-165 on the protein levels of MYC were evaluated in RPMI-8226, multiple myeloma cells." (PMID 35625675, 2022). "Most important of these are IKZF1 and IKZF3, key MM survival transcription factors which sustain the expression of myeloma oncogenes IRF4 and MYC." (PMID 36439455, 2022). "Considering the increased interest of the clinical myeloma community in tumor prevention, Vk*MYC and related models may also afford opportunities for the preclinical evaluation of candidate interventions to block the progression of high-risk MGUS and SMM to frank myeloma." (PMID 34149703, 2021). "The translocation involved a rearrangement between MYC and the IGHA2 switch region developing at a relatively early stage of disease; post-initial immortalization but before clinical myeloma." (PMID 33436579, 2021). "To define the role of NCOR2 in MM, we created NCOR2 knockout human myeloma cell lines and demonstrated that NCOR2 knockout led to high MYC expression." (PMID 34864816, 2021). "Genetically engineered mouse models (GEMMs), such as the widely known Vκ*MYC, may overcome this shortcoming because plasma cell tumors (PCTs) develop de novo (spontaneously) in a highly predictable fashion and accurately recapitulate many hallmarks of human myeloma." (PMID 34149703, 2021). "Since MYC is a direct target of IRF4 in activated B cells and myeloma, we next evaluated the expression of both proteins after treatment with PIM-Pd over time." (PMID 32987735, 2020). "Among the genes uniquely expressed following Ix-treatment in resistant myeloma were RICTOR (activated), HNF4A, miR-16-5p (activated), MYCN (inhibited), and MYC (inhibited)." (PMID 32724061, 2020). "This is further supported by a mouse model of myeloma, in which AID-induced MYC expression only results in myelomagenesis in mouse strains prone to MGUS." (PMID 31231360, 2019). "They found that SEs assist the high level transcription of genes [e.g., MYC, IRF4 (interferon regulatory factor 4), XBP1 (X-box binding protein 1), CCND2 (Cyclin D2)] that are deregulated in multiple myeloma cells." (PMID 31824865, 2019). "One possible explanation is that IRF4 targets already were up-regulated in transformed cells, such as MYC and its targets, which was a primary target of IRF4 in myeloma cells." (PMID 31666930, 2019).
multiple myeloma (continued). "Using CRISPR gene editing and/or the GO-203 inhibitor to silence MUC1 in multiple myeloma cells, MUC1-C was shown to activate MYC expression by binding to the promoter in a β-catenin/transcription factor 4-mediated mechanism." (PMID 29784646, 2018). "IRF4 directly enhances MYC, and MYC enhances IRF4, generating an autoregulatory circuit in multiple myeloma." (PMID 28910419, 2017). "Lenalidomide-induced IRF4 degradation in normal PBs and PCs is less pronounced than in OPM2 myeloma cells, possibly because IRF4 expression is deregulated in myeloma cells through continuous triggering by aberrant MYC expression." (PMID 27057635, 2016). "As a result, MYC is overexpressed following the translocations of its gene, which in turn induces overexpression of IRF4, thus forming a loop which helps the myeloma cells survive and grow." (PMID 28083618, 2016). "Global transcriptional profiling of human multiple myeloma cells treated with JQ1 reveals a strong correlation between the genes downregulated by JQ1 and the genes comprising MYC-dependent transcriptional pathways." (PMID 27827996, 2016). "The importance of MYC was further supported by an inverse correlation between IC50 of the inhibitor and the level of MYC in myeloma cell lines." (PMID 26087190, 2015). "We have previously shown that BMPs mediated growth arrest and apoptosis in myeloma cells by activation of SMAD1/5/8 and consequent downregulation of MYC." (PMID 26047946, 2015). "The frequency of MYC overexpression from secondary translocations supports its role as a progression event, as it is infrequently witnessed in MGUS but seen in 15% of myelomas and 50% of advanced disease." (PMID 24803933, 2014). "The generation of a transgenic mouse strain with sporadic c-Myc activation in GCBs (Vk*MYC), which led to a multiple myeloma phenotype, indicated that AID-mediated SHM was required for the aberrant c-Myc expression and the subsequent plasma cells expansion." (PMID 25566255, 2014). "Given that NR2E3 has been shown to repress the MYC pathway, it is plausible that NR2E3E387K may synergize with NRASQ61R to promote the development of multiple myeloma." (PMID 39809731, 2025). "Interestingly, our previous studies demonstrated that NRASQ61R alone was insufficient to induce multiple myeloma in germinal center B cells of wild-type C57BL/6 mice, but it was effective in C57BL/6 mice carrying the Vĸ-MYC insertion." (PMID 39809731, 2025). "LiCl and SB216763, both inhibitors of the serine/threonine glycogen synthase kinase 3β (GSK3β), were antiproliferative against Jurkat (acute T-cell leukemia), K562 (CML), and RPMI-8226 (myeloma) cells by promotion of proteasomal MYB degradation and suppression of BCL2, survivin, and MYC." (PMID 38835346, 2024). "Additionally, we found expression of MYC, 4EBP1, LARP1, and hnRNPC to be significantly increased in primary samples from newly diagnosed multiple myeloma (NDMM) patients compared to plasma cells (PC) from healthy donors." (PMID 38067212, 2023). "The HDAC6 inhibitor A452 in combination with Lenalidomide or Pomalidomide, displayed significantly increased synergistic anti-proliferative effects which was attributed to the augmented reduction of c-MYC, IKZF1/IKZF3 and IRF4 expression in multiple myeloma cells." (PMID 36012642, 2022). "The prognostic significances of YAP1/MYC were further confirmed in 4 external independent datasets including GEO datasets (GSE9782 and GSE2658), TCGA dataset (MMRF-COMPASS), and Oncomine dataset (Zhan myeloma 2) in over 2,000 MM patients." (PMID 35059315, 2021). "Myelocytomatosis oncogene (MYC) is a direct target of IRF4 in activated B cells and myeloma." (PMID 36045700, 2021).